FOXP3 (forkhead box P3)
Diseases named in the same sentence as FOXP3 in open-access papers (continued):
Sharing a sentence is not in itself a finding about the gene and the disease.
infection (continued). "Infection results in the percentage of CD4+CD25+Foxp3+ cells falling from 96.7% of all CD4+CD25+ cells in the CSF of EAE mice to 93.8%, and from 71.1% of all CD4+CD25hi cells in the CSF of EAE mice to 61.4%." (PMID 28975357, 2018). "We furthermore analyzed the presence of B. bronchiseptica-specific CD4+CD25+Foxp3+ Treg in infected mice, six weeks following the infection." (PMID 30200513, 2018). "First, we investigated the frequency of CD4+CD25+Foxp3+ Treg in B. bronchiseptica infected mice, in comparison to control mice on days 7, 21, and 47, post infection." (PMID 30200513, 2018). "Another interesting phenomenon, which we have demonstrated is significant reduction in FOXP3+ T cell frequency in PBMCs of patients with ITB following completion of ATT which verifies the expansion of FOXP3+ T cells during active infection." (PMID 29489879, 2018). "FoxP3DTR mice were depleted of both macrophages and FoxP3 prior to infection with HSV-IL-2 or parental virus." (PMID 28542613, 2017). "On the other hand, some reports have shown that the presence of Foxp3+ Treg cells correlates with a better outcome of the chronic phase of the infection." (PMID 28938533, 2017). "In terms of total cells, despite the infection promoting CD4+ T Foxp3+ cells expansion on both infected groups at fourth wpi, it was reduced on infected A2AR−/− mice when compared to infected WT compared with respective non-infected littermate controls." (PMID 28775724, 2017). "Since Tregs in Mavs−/− mice appeared to be losing expression of Foxp3 following infection with WNV, along with experiencing diarrhea and other signs of gastrointestinal distress, we extended our analysis of Tregs to include the mesenteric lymph nodes (MLN)." (PMID 28094802, 2017). "When we examined the frequency of CD4+Foxp3+ Tregs, we found that in contrast to pre-infection, Treg frequency was significantly reduced in Mavs−/− mice after WNV infection as compared to WT controls." (PMID 28094802, 2017). "Together, these data suggest that ex-Foxp3 Th2 cells had largely lost characteristic elements of their Foxp3-expressing past and, instead, contribute to the Th2 effector response during infection with H. polygyrus, particularly during proficient immunity." (PMID 28507062, 2017). "We evaluated the effect of treatment with BNZ in IL-10, TGF-β and Foxp3 gene expression during the acute phase of infection." (PMID 29255475, 2017). "The numbers of CD4+CD25+Foxp3+ T cells were similar in naïve B6 and Irf8-/- mice, but this population expanded early during infection in both B6 and Irf8-/- mice." (PMID 28968468, 2017). "Low numbers of IL-10–expressing Foxp3+ Treg cells were detected in the lungs throughout infection (<0.15 × 105 cells per lung)." (PMID 28584007, 2017). "Here we link the increase in Treg frequency and Treg CD25, CTLA-4 and FOXP3 expression to the infection-induced release of IL-2, detectable in the serum." (PMID 28815218, 2017). "It is well established that natural regulatory T (Foxp3+ Treg) cells suppress the host inflammatory responses during infection and thereby maintain physiological homeostasis of host immunity." (PMID 28286572, 2017). "In this sense, it has been shown that patients in an indeterminate state of infection possess a higher number of Foxp3+ regulatory cells as compared with symptomatic patients." (PMID 28938533, 2017). "Some 20 days after infection the size of Foxp3+ Tregs pool in P. yoelii 17XNL-infected NOD mice was significantly increased by almost 100% (∗p = 0.045)." (PMID 28074170, 2016). "pDC-depleted mice showed significantly lower frequency and number of pulmonary CD4+CD25+Foxp3+ Treg cells than IgG-treated control mice (left and central panels) after 2 weeks of infection." (PMID 27992577, 2016). "In particular, NK‐cell depletion also enhanced the proportion of CD4+ CD25+ Foxp3+ T cells in infection sites (lung tissues) and mediastinal lymph node cells at day 6 after infection." (PMID 27028780, 2016).
infection (continued). "When we analyzed the single-cell suspensions from dissociated lungs after Ad Foxp3-EGFP or Ad-EGFP infection, Foxp3 was expressed in CD326+ epithelial cells, but not in CD4+ or CD8+ cells." (PMID 27633092, 2016). "Our results on regulation of SR T cells during persistence also corroborated control of transferred SR CD4+ T cell proliferation by Foxp3+ Tregs during a heterologous MHV infection." (PMID 27708643, 2016). "To assess the impact of Treg depletion during the chronic phase of infection, we made use of transgenic Foxp3.LuciDTR mice backcrossed to the C57BL/6 background." (PMID 26286232, 2016). "T follicular regulatory (Tfr) cells are a subset of Foxp3+ regulatory T (Treg) cells that form in response to immunization or infection, which localize to the germinal centre where they control the magnitude of the response." (PMID 26818004, 2016). "FACS measurement of Foxp3+ Tregs frequency in the blood of infected NOD mice at day 14 after infection showed a 50% to 65% increase as compared to their own controls prior to infection." (PMID 28074170, 2016). "In a murine model, Foxp3+ T-reg accumulated in the lung and pulmonary lymph nodes within weeks following aerosol infection with MTB." (PMID 27441095, 2016). "This increase continued through day 14 post-infection resulting in more than an eight-fold increase in total CD4+CD25+FoxP3+ T cells." (PMID 27175511, 2016). "Within the MLN, infection of BALB/c mice drove increased Foxp3+ Treg frequency, while C57BL/6 mice had constitutively high levels, which did not rise significantly following infection." (PMID 26286232, 2016). "A reduction in Tr1 (CD4+FOXP3-PD1hiIL10+) cells was also observed at three weeks post infection, closely mirroring the predicted 50% reduction at that time." (PMID 27936058, 2016). "In support, infection with T. spiralis is reported to be accompanied by the accumulation of FoxP3+ Treg cells in the infected muscles during the chronic phase of infection." (PMID 27802332, 2016). "It thus remains to define what parasite antigens at what stage of infection are responsible for upregulation of parasite-specific Foxp3+ Tregs." (PMID 28074170, 2016). "An enhancement in the co-expression of CD25+GITR+ or CD25+CD62L+ was also observed after infection among CD4+Foxp3+ cells." (PMID 26745276, 2016). "The proportion and number of CD4+ CD25+ Foxp3+ T cells was significantly higher in NK cell‐depleted mice than control mice at day 6 and 12 after infection." (PMID 27028780, 2016). "The number of induced Treg cells (CD4+Foxp3+) was higher in the Lb than in the La infection at 4 weeks PI but decreased in the DLN of mice infected with Lb during the evolution of the infection." (PMID 27073297, 2016). "One single administration of 1 mg depleting Ab immediately before infection resulted in 70% depletion of CD4+Foxp3+ Tregs in the blood at steady state and following infection." (PMID 26286232, 2016). "Validation of Foxp3 expression in DEREG mice thus facilitated characterization of Foxp3+ Treg kinetics during the course of infection." (PMID 27708643, 2016). "In mammals, IL-6 induction through STAT3 phosphorylation downregulates FOXP3 and blocks Treg cell differentiation while maintaining the Th17 response in order to continue dealing with the infection." (PMID 27069644, 2016). "In fact, most of the T cell-derived IL-10 during infection was produced by FoxP3- IFN-γ+ cells, and was reflected by IL-10 secretion from E/S-stimulated LI LP cells." (PMID 25942314, 2015). "Later on in infection, at week 10, the increase in the mRNA levels of Tbet, GATA3 and RORγC paralleled the reduction in expression levels of the Treg-associated molecules Foxp3, PD-L1, CCR5, CCR6 and Granzyme B." (PMID 26512987, 2015). "Subtle changes or down regulation in TLR transcription, Th17 cytokines and FoxP3 are indicative of the silent establishment of infection that Leishmania is renowned for." (PMID 26465878, 2015).
infection (continued). "Transcription of TLR2 and TLR9, together with FoxP3, were all up regulated in the earlier stages of infection when compared with the controls." (PMID 26465878, 2015). "Expression of H2-T23 (Qa-1/HLA-E) and FOXP3 was induced in thymus and liver of C57BL/6 mice, which exhibited defective control of viral load, suggesting a higher susceptibility to YFV17D infection." (PMID 26457200, 2015). "At 15 months post infection, strong positive correlation was revealed in the skin for both IL-17 and FoxP3 transcription (rs = 1, p <0.001 in both instances)." (PMID 26465878, 2015). "The rapid recruitment and activation of Foxp3+ Treg cells is a feature of infections with parasitic nematodes (7, –, 9, 14, 26)." (PMID 26195548, 2015). "Only TLR9 was significantly up regulated in the early stages of infection and marginal significance was revealed for FoxP3 when both Groups 1 and 2 were compared with controls." (PMID 26465878, 2015). "Consistent with the minimal contribution from residual T cells following lethal irradiation, we verified that the CD45.2:CD45.1 ratio in peripheral blood was 1:1, with similar proportions of CD4, CD8 T cells and Foxp3+ Tregs prior to infection." (PMID 25590581, 2015). "The reduction in the levels of Treg-associated molecules, such as Foxp3, CCR5, CCR6, PD-L1 and Granzyme B, maintained even after week 10 post-infection, corroborates the beneficial effects of the early anti-CD25 treatment." (PMID 26512987, 2015). "CD25+Foxp3+CD4+ Tregs increased from 7 days post-infection until 28 days post-infection in the lungs for all Mtb strains." (PMID 26675186, 2015). "Similar to what we found for CXCR5+ T cell responses, percentages of FoxP3+ cells were higher prior to infection, and at day 8 pi in GITRL tg mice compared to their WT counterparts." (PMID 25738498, 2015). "Mice receiving CD4+Foxp3- T cells showed significantly higher numbers of lymphocytes, macrophages and granulocytes in the lungs at weeks 2 and 6 post-infection as compared to mice receiving Treg cells alone or in combination with CD4+Foxp3- T cells." (PMID 26512987, 2015). "Both CD4+Foxp3− effector cells and CD4+Foxp3+ Tregs responded to infection by expressing IL-17A in the draining axillary lymph nodes (ALN), cervical lymph nodes (CLN) and MOIL in infected mice." (PMID 25790134, 2015). "Mice reconstituted with CD4+ Foxp3- T cells prior to infection showed a mean survival of 126.8 days." (PMID 26512987, 2015). "Western blot analyses of cell lysis confirmed the production of Foxp3-GFP fusion protein in Foxp3 engineered MSC compared with MSC transfected with an empty vector 96 h after infection." (PMID 26293578, 2015). "The parasite burden in the lymph node was also increased between the two infected groups and taken together these findings suggest that FoxP3 is required to control the infection." (PMID 26465878, 2015). "In contrast a regulatory response, characterized by the accumulation of CD4+CD25+Foxp3+ Treg cells was detected between days 8 and 10, and preceded by a slight suppression between days 4 and 7 post-infection." (PMID 26230099, 2015). "In S. ratti and T. muris infections, Foxp3+ Treg cells act very early, and protective immunity can only be restored if they are depleted prior to day 4 or day 9 of infection, respectively." (PMID 26195548, 2015). "The advantage over the traditional Treg cell characterization by CD4+CD25hiCD127loFOXP3+ is that conventional CD4 T cells with an up-regulated CD25 and FOXP3 expression due to the generalized, infection-related immune activation are excluded from the analysis." (PMID 26633181, 2015). "Following infection with lentiviruses, FOXP3-transduced cells were tested for potential immunosuppressive activities." (PMID 26437631, 2015). "CD4+Foxp3+ T-cells accumulate at sites of infection and prevent efficient clearance of infection in mice infected with M. tb." (PMID 25659138, 2015).
infection (continued). "The sum of these data suggest a novel role for human CD4+CD25+Foxp3+ cells in protection against infection and identify a new molecule, D4GDI, through which such protection is mediated." (PMID 25659138, 2015). "The sum of our studies in humans and murine models of infection suggest that D4GDI produced by CD4+CD25+Foxp3+ T-cells has a previously undescribed positive effect on immunity by enhancing host antimicrobial activity." (PMID 25659138, 2015). "One study showed that the expression of FOXP3, a marker for T-regulatory cells, was increased in children with clinical signs of trachoma in whom infection had resolved." (PMID 24606636, 2014). "LAP+ Tregs suppressed the proliferation of activated T cells but not of naïve T cells in a TGF-β–dependent manner and mediated infection tolerance by converting Foxp3-negative Tregs to functionally active Foxp3-positive Tregs." (PMID 25268580, 2014). "To do this we used immunohistochemistry to examine the frequency of FoxP3+ T cells in the T zones of infected mice on day 5 after infection, when pathogen burdens were similar in mice that received one or both pathogens." (PMID 25474738, 2014). "Analysis of outcomes on day 35 postinfection supported a slightly greater role for FoxP3+ Tregs on moderating worm burdens if depletion was done over the first 8 days of infection." (PMID 24942690, 2014). "Regulatory molecules like Foxp3 and TGFβ1 indeed have been reported to regulate immune responses during infection thereby preventing excessive inflammation and tissue damage." (PMID 24885723, 2014). "Expansion of Foxp3+ Treg was comparable in both strains displaying maximal numbers at day 2 p.i. in the lymph nodes draining the site of infection and at day 14 p.i. in the lymph nodes draining the intestine i.e. the environment of parasitic adults." (PMID 24516385, 2014). "The up-regulation of pro-inflammatory gene expression was paralleled by a decrease in transcription levels of FoxP3 that stayed between 0.4 and 0.5 from day 8 to day 29 post-infection." (PMID 25919005, 2014). "CpG pre-conditioning also decreased the percentage of CD45+CD4+CD3+CD25+FoxP3+ regulatory T cells in spleen and brain 42 h after infection." (PMID 24456653, 2014). "In naturally exposed Gambians CD4+FOXP3+CD127lo Tregs during acute infection were inversely correlated with memory responses at 28 days, suggesting suppression of immune memory." (PMID 25309517, 2014). "A role for FoxP3+ Tregs cells in controlling pathology was shown following a primary infection with H. polygyrus bakeri in DEREG mice." (PMID 24942690, 2014). "CCR5-/- mice were extremely susceptible to infection, presenting higher parasite load and lower tissue expression of IL-12p40, IFN-γ, TNF, IL-6, iNOS, Foxp3, T-bet, GATA-3 and PPARα." (PMID 25119429, 2014). "It has been shown that CD4+CD25+Foxp3+-deficient mice are hyperactive to intestinal commensal flora and would develop IBD triggered by infection." (PMID 25475342, 2014). "The percentage of FoxP3+CD4+ T cells observed at day 20 post infection (p.i.)was reduced in the lungs and spleen of M. bovis BCG infected mice compared to non-infected controls." (PMID 25050936, 2014). "This work demonstrates, for the first time, that disseminated infection with C. albicans drives the expansion of complex Foxp3+ cell populations, including cells with nTreg-, iTreg-, and Th17-cell characteristics." (PMID 24435677, 2014). "Consistent with this, we found that infected p110δD910A mice have significantly lower numbers of CD4+CD25+Foxp3+ (Tregs) in their spleens throughout the course of infection compared to their WT counterpart mice." (PMID 24945303, 2014). "In mice with Candida albicans infection, a reduction in the FOXP3+ Treg level effectively controlled the infection, however, simultaneously enhanced the pathological injury that was induced by the gastrointestinal inflammation." (PMID 24944616, 2014).
infection (continued). "While IL-2 and IL-17 expression by MLNC Foxp3+ Treg cells was very low in both genotypes of naive mice, infection induced a significant increase in Foxp3+IL-17+ cell numbers in the BALB/c strain." (PMID 24185641, 2014). "For example, Foxp3+ cells accumulate at the pathologic sites of infection and play a role in both murine and human VL." (PMID 24945303, 2014). "Protection against EAAI to OVA was stronger during the chronic phase of infection and associated with increased numbers of splenic CD4+CD25+Foxp3+ Treg cells with suppressive activity." (PMID 23365718, 2013). "Throughout the infection there was an increased proportion of CD4+ cells expressing Foxp3 in B6.CCR7-/- mice." (PMID 24205367, 2013). "In the natural infection model with S. mansoni, dramatic and progressive increases in the expression of FoxP3 mRNA were observed in the liver and spleen, with peak expression occurring at the 16 week granuloma downmodulated stage and highest in the liver." (PMID 23429492, 2013). "Lungs were harvested at the indicated time points post-infection, and flow cytometric analysis was performed to determine the percentage of Foxp3+ cells out of the CD4+ T cell population." (PMID 23785280, 2013). "Following infection with Schistosoma mansoni or Leishmania major, robust Th2 or Th1- responses develop, accompanied by the recruitment of Foxp3+ Treg cells." (PMID 23825948, 2013). "For instance, infection of BALB/c mice with Brugia pahangi third-stage larvae (L3) resulted in expansion of a population of CD4+CD25+ T cells which was highly enriched in Foxp3 and IL-10 gene expression." (PMID 23365718, 2013). "Both IL-10-producing CD5+ B cells and FoxP3+ TREG cells are stimulated by infection with schistosomes." (PMID 23429492, 2013). "One study showed that the expression of FOXP3, used as an indicator of regulatory T cells, was increased in children who had clinical signs of trachoma but in whom infection had resolved." (PMID 23457650, 2013). "The percentage of BrdU+Foxp3+ cells within the MLN significantly increased in both strains of mice upon infection demonstrating that Foxp3+ Treg cells proliferate in response to H. polygyrus infection." (PMID 23319295, 2013). "Based on recent data about T reg expansion during infection, Foxp3 expressing CD4+CD25+ T cells were found responsible for TGF-β and CD4+CD25−Foxp3− T cells for IL-10 production." (PMID 23638195, 2013). "In a rat model, the infection with T. spiralis is accompanied with the increase proportion of Foxp3+ Treg cells." (PMID 23365718, 2013). "Given that ICOS was dispensable for Foxp3+ Treg-cell proliferation during infection, we asked if the defective Foxp3+ Treg-cell responses evident in ICOS−/− mice were due to impaired survival." (PMID 23319295, 2013). "This reduction in the degree of MAIDS seen was apparently due to the observed expansion of a protective CD8+ CTL population, which had previously been suppressed by FoxP3+ Tregs and/or PD-1 following the infection of intact, un-manipulated B6 mice." (PMID 23680027, 2013). "S. mansoni egg antigens can downmodulate immune responses by activating Foxp3+ regulatory T cells and inducing IL-10, ameliorating the pathology of infection and reducing the response to other antigens in the lung." (PMID 23637937, 2013). "In contrast, BrdU uptake by CD4+Foxp3− Teff cells at day 7 of infection was severely diminished in ICOS−/− mice." (PMID 23319295, 2013). "The expansion but low IL-10 expression of FoxP3+ TREG cells was also observed in a separate study of the natural infection model." (PMID 23429492, 2013). "Regulatory T cells expressing CD4+/CD25+/FoxP3+ increased significantly over the course of infection." (PMID 23555767, 2013). "Gene expression studies have shown increased expression of IFNγ, IL12p40, Perforin, IDO, IL-4, IL-10, and forkhead box p3 (FOXP3) in infection and/or disease, with levels generally being highest if both were present." (PMID 23457650, 2013).